REV1 (REV1 DNA directed polymerase)
Diseases named in the same sentence as REV1 in open-access papers (continued):
Sharing a sentence is not in itself a finding about the gene and the disease.
lung carcinoma (continued). "To identify the specific molecules that regulate REV1, we first treated lung cancer cells with MG132 and found that REV1 expression was significantly upregulated, suggesting that REV1 may be regulated by the ubiquitin-proteasome system." (PMID 38802791, 2024). "These experiments suggest that targeting REV1 can enhance the radiosensitivity of lung cancer cells in vivo, but this effect is not observed in vitro." (PMID 38802791, 2024). "REV1 proteins were not expressed or medium expressed in normal lung tissues, while high protein expressions of REV1 were expressed in lung cancer tissues." (PMID 36246647, 2022). "Since TLS is abnormally activated in lung cancer and REV1 is the central member of the TLS polymerase family, we speculated that the regulatory effect of REV1 on SERTAD2 is related to the biological process of TLS." (PMID 35115490, 2022). "Compared with adjacent tissues, REV1, Rad18, RPA32 and REV7 showed higher expression in lung cancer tissues, indicating that TLS may be abnormally activated in lung cancer." (PMID 35115490, 2022). "Aberrantly expressed REV1 acts as a scaffolding protein to assist the interaction between the Rad18 E3 ubiquitin ligase and CTH, promoting CTH ubiquitination-mediated degradation and inducing remodeling of the amino acid metabolic microenvironment, leading to lung cancer radioresistance." (PMID 38802791, 2024). "To determine the specificity of JH-RE-06, we used JH-RE-06 to treat REV1 silencing cells and found that the inhibitory effect of REV1 silencing on the growth and proliferation of lung cancer cells could not be further enhanced, indicating that JH-RE-06 functions in a REV1-dependent manner." (PMID 35115490, 2022).
lymphoma (7 papers, 2011 to 2023). A malignant (clonal) proliferation of B- lymphocytes or T- lymphocytes which involves the lymph nodes, bone marrow and/or extranodal sites. "We also found that relative to normal tissue controls, REV1 expression was lower in breast, ovarian cancer and lymphoma tissues." (PMID 36246647, 2022). "We validated the absence of REV1 protein in Rev1-KO lymphomas by western blot, and analyzed the sensitivity of these isogenic WT, PcnaK164R and Rev1-KO lymphomas to cisplatin." (PMID 35819193, 2022). "In vivo, we noted a slight delay in the outgrowth of Rev1-KO lymphomas compared to WT controls." (PMID 35819193, 2022). "Furthermore, of this gene list, 3 are also in the list of genes with known links to CHK1 (Poli, Rev1, Ddb2) we identified as having altered expression in Eμ-Myc/RelaT505A lymphomas." (PMID 36240065, 2022). "To examine whether REV1 is required in tolerating cisplatin lesions in cancer cells, we genetically ablated Rev1 in murine lymphoma cells that were described previously using the same CRISPR/Cas9 targeting strategy as used for the Rev1-KO mice." (PMID 35819193, 2022). "The same study also showed that REV1 suppression in lymphoma cells inhibited resistance formation after cyclophosphamide treatment in vitro and improved cyclophosphamide-based chemotherapy of lymphomas in vivo." (PMID 22047021, 2011). "Consistent with our in vivo data and in vitro MEF data, PcnaK164R lymphoma cells were very sensitive to cisplatin, while Rev1-KO lymphomas were indistinguishable from WT." (PMID 35819193, 2022). "Similarly, using a preclinical mouse model of Burkitt's lymphoma, it was shown that suppression of both REV1 and REV3 expression, sensitized lymphomas to cisplatin." (PMID 22047021, 2011). "Moreover, as expected, we did not observe effects of the REV1i on WT or REV1 mutant MEFs and lymphomas or PreBs (data not shown)." (PMID 35819193, 2022). "Moreover, once established, Rev1-KO lymphomas did not grow slower than WT lymphomas, arguing against tumor growth defects." (PMID 35819193, 2022). "An analysis of the mRNA levels of uracil excision repair factors in CAG-A3B lymphomas indicates positive associations between APOBEC signature enrichment and uracil DNA glycosylase 2 (Ung2), AP endonuclease 1 (Apex1), and X-ray repair cross-complementing protein 1 (Xrcc1), but not with Rev1." (PMID 36865194, 2023). "Interestingly, RNA-seq data from CAG-A3B lymphomas indicate positive associations between APOBEC mutation signature enrichment scores and mRNA levels for Ung2, AP endonuclease 1 (Apex1), and X-ray repair cross-complementing protein 1 (Xrcc1) but not for Rev1." (PMID 37797615, 2023).
melanoma (6 papers, 2018 to 2022). A malignant, usually aggressive tumor composed of atypical, neoplastic melanocytes. "In both human and mouse cell lines, JH-RE-06, a small molecule that binds to the C-terminal domain of Rev1 and blocks interaction with the Rev7 subunit of Pol ζ, sensitised melanoma cells to cisplatin, and reduced drug-induced mutagenesis." (PMID 35198436, 2021). "The expression of REV1 in multiple tumour and normal tissue types from the Oncomine database revealed that expression of this gene was elevated relative to normal tissue controls for brain, renal, prostate cancers, melanoma, myeloma and sarcoma." (PMID 36246647, 2022). "Polymorphisms in REV1 and POLI, leading to single amino acid substitutions in Rev1 and Pol ι, were associated with increased risk of squamous cell carcinoma and adenocarcinoma, respectively, while POLH polymorphisms are associated with increased risk of malignant melanoma." (PMID 35198436, 2021). "These correlation results suggest a strong contribution of REV1, UNG, and possibly APOBEC3A to overall mutagenesis in sarcoma, melanoma, and renal cell carcinoma, respectively." (PMID 29642934, 2018).
abortion (5 papers, 2014 to 2024). the ending of pregnancy by removing a fetus or embryo before it can survive outside the uterus. "Among the 20 AEs, abortion AE is the only one that has been reported to the vaccination with Rev1." (PMID 29867505, 2018). "For example, when vaccinated Rev1 to the pregnant ewes with dosage of 1 × 109 CFU, abortions occurred later at surprisingly severe rates (90.9%), while in the 1 × 108 CFU ewes group, the abortion rate was only 20%." (PMID 29867505, 2018).
ovarian carcinoma (5 papers, 2015 to 2024). A malignant neoplasm originating from the surface ovarian epithelium. "The goal of the current study was to examine single nucleotide polymorphisms (SNPs) in circadian genes BMAL1, CRY2, CSNK1E, NPAS2, PER3, REV1 and TIMELESS and downstream transcription factors KLF10 and SENP3 as predictors of risk of epithelial ovarian cancer (EOC) and histopathologic subtypes." (PMID 26807442, 2015). "The elevation expression of REV1 to be significantly linked with a poorer prognosis in gastric cancer [OS: HR, 1.4, 95% CI, 1.11–1.76, p = 0.0038; post progression survival (PPS): HR, 1.45, 95% CI, 1.11–1.9, p = 0.0069] and ovarian cancer (PPS: HR, 1.35, 95% CI, 1.04–1.75, p = 0.024)." (PMID 36246647, 2022). "REV1 is necessary for gap suppression and tolerance of DNA damage from both intrinsic sources and ATR/WEE1-inhibition in ovarian cancer cells." (PMID 38438348, 2024).
Fanconi anemia (4 papers, 2013 to 2026). Fanconi anemia (FA) is a hereditary DNA repair disorder characterized by progressive pancytopenia with bone marrow failure, variable congenital malformations and predisposition to develop hematological or solid tumors. "The diseases associated with REV1 encompass the variant form of xeroderma pigmentosum and Fanconi anemia." (PMID 38840241, 2024). "Protein interaction analysis indicates that this “genic signature” (Dclre1a, Rev1, Xpa, Pms2, Brca2, Parp2, Smc3, Nbn, Bax) is mainly involved in the Fanconi anemia pathway and homologous recombination repair." (PMID 34573315, 2021). "The Fanconi anaemia (FA) pathway constitutes a central genome maintenance system that orchestrates the repair of DNA interstrand crosslinks (ICLs) through the coordinated monoubiquitination of FANCI and FANCD2, followed by recruitment of repair effectors such as BRCA1, REV1, and ERCC1." (PMID 41486508, 2026).
lung adenocarcinoma (4 papers, 2021 to 2022). A carcinoma that arises from the lung and is characterized by the presence of malignant glandular epithelial cells. "In colon adenocarcinoma and rectum adenocarcinoma and lung adenocarcinoma, low expression of REV1 may suggest resistance to drugs in certain pathways." (PMID 36246647, 2022). "Consistent with the results in databases, we found that the expression of REV1, Rad18 and RPA32 was dramatically upregulated in lung adenocarcinoma tissues, as shown by immunohistochemical (IHC) staining of 5 pairs of lung adenocarcinoma and adjacent tissues." (PMID 35115490, 2022). "Interestingly, our analysis (described in the previous section) finds that REV1 expression levels are negatively correlated with SNV burden in human lung adenocarcinomas from smokers, suggesting that the role of REV1 in tumor mutagenesis may be context dependent." (PMID 34663880, 2021).
fibrosarcoma (3 papers, 2021). A malignant mesenchymal fibroblastic neoplasm affecting the soft tissue and bone. "Two such compounds, 4 and 5, have been reported that bind to the Rev1-CT, preventing the recruitment of Pol ζ to Rev1, and sensitising fibrosarcoma cell lines to cisplatin and to UV radiation." (PMID 35198436, 2021).
Splenomegaly (3 papers, 2018 to 2025). Abnormal increased size of the spleen. "In 16M and Rev1 groups, the splenomegaly was also accompanied by granulomas, leading to a ten-fold increase in the spleen weight at the end of pregnancy." (PMID 35335603, 2022). "Mice infected with B. melitensis 16M or Rev1 displayed a significative increase in IL-12 and IFN-γ at 5 days PI, decreasing thereafter, more markedly in Rev1; IL-12 peaked again at the end of pregnancy, overlapping the highest peak of splenomegaly." (PMID 35335603, 2022). "PBS inoculated females also showed a peak of physiological splenomegaly at 10 DG (0.27 g/spleen); nevertheless, splenomegaly induced by B. melitensis 16M and Rev1 exceeded six times these values at late gestation." (PMID 35335603, 2022).
cervical cancer (2 papers, 2022). A primary or metastatic malignant neoplasm involving the cervix. "To determine if the same was true for TLS genes other than the TLS polymerases (POLH, POLI, POLK, REV1, and REV3L), we segregated the cervical cancers in the TCGA database based on whether they did or did not have increased expression of at least one TLS gene." (PMID 36266721, 2022).
infertile (2 papers, 2022 to 2024). "Our findings demonstrate that REV1 is required for both human PGCLC and mouse PGC development, indicating a conserved embryonic cause of infertility." (PMID 38702312, 2024). "Third, we noted that PcnaK164R mice, but not Rev1-mutant mice were infertile." (PMID 35819193, 2022).
migraine (2 papers, 2024 to 2025). "The REV1 gene is located on chromosome 2q11.2, and MR analysis confirmed a causal relationship between REV1 and migraine (p < 0.05)." (PMID 40994718, 2025). "Cross-tissue TWAS analysis, along with validation through single-tissue TWAS and MAGMA, led to the identification of two migraine susceptibility genes (REV1 and SREBF2), which were further substantiated by MR and colocalization analyses." (PMID 38840241, 2024). "We sought to explore the potential interactions among SREBF2 or REV1 and previously identified genes associated with migraine susceptibility." (PMID 38840241, 2024). "In this study, the MR results indicated a significant causal association between REV1 expression and a reduced risk of migraine." (PMID 38840241, 2024). "MR analyses confirmed a causal relationship between REV1 and migraine (p < 0.05)." (PMID 38840241, 2024). "The inverse correlation between REV1 expression and migraine risk may be attributed to its regulated role in DNA damage repair, although further studies are required for confirmation." (PMID 38840241, 2024). "REV1 may reduce the migraine risk by regulating DNA damage repair, while SREBF2 may increase the risk of migraine by regulating cholesterol metabolism." (PMID 38840241, 2024). "The REV1 gene is located on chromosome 2q11.2, and FUSION analysis revealed its significant association with migraine in Whole_Blood and Cells_Cultured_fibroblasts." (PMID 38840241, 2024). "Therefore, further investigation is required to elucidate the role of SREBF2 and REV1 in migraine pathogenesis." (PMID 38840241, 2024). "Through cross-tissue TWAS analysis and rigorous validation, two genes (REV1 and SREBF2) associated with migraine risk were identified, which have not been previously reported." (PMID 38840241, 2024). "Lastly, the expression levels of REV1 and SREBF2 in tissues previously more closely associated with migraine, such as cerebral arteries, were not able to be assessed and validated in the current dataset." (PMID 38840241, 2024). "Although there was no prior empirical evidence linking REV1 to migraine, we extrapolated conclusions from its functional characteristics." (PMID 38840241, 2024).
Thyroid Carcinoma (2 papers, 2021 to 2022). "Conversely, high expression of REV1 in acute myeloid leukemia, brain lower grade glioma, small cell lung cancer and thyroid carcinoma may indicate resistance to drugs in certain pathways." (PMID 36246647, 2022).
abscesses (1 paper, 2019). "Only mild local abscesses were caused by Rev1::gfp in some lambs, that resolved spontaneously few weeks after vaccination, as reported to Rev1." (PMID 30375177, 2019).
acute lymphoblastic leukemia (1 paper, 2022). Leukemia with an acute onset, characterized by the presence of lymphoblasts in the bone marrow and the peripheral blood. "In acute lymphoblastic leukemia, REV1 expression is negatively correlated with IC50 of drugs of Genome integrity and metabolism pathways while positively correlated with IC50 of drugs of RTK signaling pathway." (PMID 36246647, 2022).
arthropathy (1 paper, 2018). Any disorder of the joints. "Based on our study, in addition to abortion and arthropathy, no other AEs were reported to associate with S19 and/or Rev1 in animals." (PMID 29867505, 2018).
bone osteosarcoma (1 paper, 2021). A usually aggressive malignant bone-forming mesenchymal neoplasm arising from the bone. "Knockdown of REV1 expression using miR-96 contributed to cisplatin sensitization in bone osteosarcoma cells with intact HR repair, as well as in BRCA1-deficient breast cancer and BRCA2-deficient ovarian cancer cell lines with compromised HR pathways." (PMID 35198436, 2021). "Of note, inhibition of the Rev1-CT/RIR interaction was synergistic with the ATM and ATR inhibitor VE-821 and the Wee1 inhibitor MK-1775, leading to the formation of daughter strand gaps (DSGs) in replicating DNA, and sensitising bone osteosarcoma and colon cancer cells to these agents." (PMID 35198436, 2021).
breast tumor (1 paper, 2019).
chronic bronchitis (1 paper, 2022). A type of chronic obstructive pulmonary disease characterized by chronic inflammation in the bronchial tree that results in edema, mucus production, obstruction, and reduced airflow to and from the lung alveoli. "Regarding “Workplace very dusty: Sometimes” (that has a causal effect on “Condition that has ever been diagnosed by a doctor: Emphysema or chronic bronchitis”) the most statistically significant pathway is “Translation synthesis by REV1”, involving the REV1 gene." (PMID 36395113, 2022).
colon cancer (1 paper, 2018). "A proximity ligation assay (PLA) was used to investigate interactions between REV3L, REV1, and MAD2L2 in normal (CCD-18Co) and colon cancer cells." (PMID 29435169, 2018). "However, the number of interactions between REV3L and REV1, REV3L and MAD2L2, and REV1 and MAD2L2 were reduced to 44/cell, 27/cell, and 26/cell, respectively, in HCT-116 colon cancer cells and to 19.2/cell, 59/cell, the 51/cell in DLD-1 colon cancer cells." (PMID 29435169, 2018).
Diabetes (1 paper, 2022). "ANKRD12, NME7 and REV1 showed a 1.6 to 2.5-fold decreased expression in kidney glomeruli from individuals with DKD compared to healthy living donors (p < 0.01) in the Woroniecka Diabetes Dataset21." (PMID 36550108, 2022).
gastric cancer (1 paper, 2022). A primary or metastatic malignant neoplasm involving the stomach. "REV1 expression is significantly correlated with different prognosis in colorectal, ovarian, lung, breast, and gastric cancer." (PMID 36246647, 2022).
HCMV infection (1 paper, 2025). "We previously found that TLS polymerases are involved in HCMV infection, whereby Y-family insertion polymerases η, κ, and ι restricted replication, and Rev1 and ζ were required for efficient virus replication." (PMID 40130902, 2025).
HIV-1 infection (1 paper, 2015). The type species of lentivirus and the etiologic agent of acquired immunodeficiency syndrome (AIDS). "Since these clades have been estimated to account for as many as 75% of all HIV-1 infections worldwide, it seems clear that a significant fraction of naturally occurring HIV-1 strains encode a rev1-vpu fusion gene." (PMID 26554585, 2015). "To examine possible effects of the rev1-vpu fusion gene under conditions that more closely resemble HIV-1 infection in vivo, we also infected human tonsillar explant cultures that promote HIV-1 replication in the absence of exogenous stimuli." (PMID 26554585, 2015). "To examine whether the rev1-vpu fusion gene was under positive or negative selection during the course of HIV-1 infection, we analyzed the viral quasispecies in eight longitudinally sampled patients who were acutely infected with clade A or C strains." (PMID 26554585, 2015).
intestinal tumor (1 paper, 2022). "Studies have shown that REV1 may play an oncogenic role in lung and intestinal tumor." (PMID 36246647, 2022).
kidney adenocarcinoma (1 paper, 2022). "REV1 proteins were high expressed in normal kidney tissues, while low protein expressions of REV1 were expressed in kidney adenocarcinoma tissues." (PMID 36246647, 2022).
kidney failure (1 paper, 2022). An acute or chronic condition that is characterized by the inability of the kidneys to adequately filter the blood. "Furthermore, we show that methylation levels at 21 of these sites predicted the development of kidney failure in T1D (p < 0.05) and found evidence for causal effects for the methylation of cg23527387 within the REV1 gene." (PMID 36550108, 2022).
non-small cell lung carcinoma (1 paper, 2018). A group of at least three distinct histological types of lung cancer, including non-small cell squamous cell carcinoma, adenocarcinoma, and large cell carcinoma. "Expression levels of UNG and REV1 were significantly positively correlated in non-small cell lung cancer cell lines (NSCLC; ρ = 0.344, padj = 2.98 × 10−5, n = 186, Ntests = 230)." (PMID 29642934, 2018).
rectal cancer (1 paper, 2018). A primary or metastatic malignant neoplasm that affects the rectum. "The variant GG genotype in REV1 rs3087399 was associated with a decreased risk of rectal cancer in the codominant and recessive model (GG vs. AA; OR 0.13; 95% CI 0.02–0.96; p = 0.05; and GG vs. AA+AG; OR 0.12; 95% CI 0.02–0.90; p = 0.04)." (PMID 30591675, 2018).
skin cancer (1 paper, 2023). "It was initially expected that less skin cancer would be induced by UV radiation because of the low-level error-prone activity of the hypomorphic Rev1." (PMID 37087526, 2023).